CAMKV (CaM kinase like vesicle associated)
Description:
Does not appear to have detectable kinase activity.
Synonyms: MGC8407; VACAMKL; 1G5
Tractability: Small molecule: it belongs to a druggable protein family. Antibody: UniProt places it where antibodies can reach, with medium confidence; its Gene Ontology location is reachable by antibodies, with medium confidence. PROTAC: ubiquitination databases record sites on it; its protein half-life has been measured.
Gene: Protein-coding gene on chromosome 3 (49,857,214 to 49,869,935, reverse strand). Ensembl gene ENSG00000164076.
Subcellular location: Cell membrane; Cytoplasmic vesicle membrane
Subcellular location (Human Protein Atlas): Nucleoplasm; Cytokinetic bridge
Gene Ontology:
Molecular function: calcium/calmodulin-dependent protein kinase activity; calmodulin binding; ATP binding; protein kinase activity
Biological process: signal transduction; modulation of chemical synaptic transmission; regulation of modification of postsynaptic structure
Cellular component: cytoplasm; synapse; cytoplasmic vesicle membrane; glutamatergic synapse; plasma membrane
Genetic constraint (gnomAD): Loss-of-function variants: 5 observed, 51.95 expected, observed/expected ratio (o/e) 0.0962, 90% interval 0.049 to 0.2. The upper end of that interval is the gene's LOEUF score, 0.2, which puts it in group 1 of 6, group 1 being the genes least tolerant of losing a copy. Missense variants: 361 observed, 668.18 expected, observed/expected ratio (o/e) 0.54, 90% interval 0.5 to 0.59. Synonymous variants: 229 observed, 260.04 expected, observed/expected ratio (o/e) 0.88, 90% interval 0.79 to 0.98.
Homologues: Orthologues: chimpanzee CAMKV (99% identical), macaque CAMKV (99% identical), rabbit CAMKV (95% identical), mouse Camkv (95% identical), pig CAMKV (95% identical), guinea pig CAMKV (95% identical), rat Camkv (93% identical), dog CAMKV (90% identical), tropical clawed frog camkv (62% identical), zebrafish camkvb (62% identical), zebrafish camkva (61% identical). Paralogues in human: CAMK1G (31% identical), CAMK1 (31% identical), CAMK1D (30% identical), PNCK (28% identical), DCLK2 (26% identical), PSKH1 (25% identical), DCLK1 (24% identical), CAMK2A (24% identical), CAMK2D (24% identical), CAMK2B (24% identical), PSKH2 (24% identical), CAMK2G (24% identical), and 10 more.
Diseases named in the same sentence as CAMKV in open-access papers:
CAMKV is named in the same sentence as 16 diseases in open-access papers, as found by Europe PMC text mining. Sharing a sentence is not in itself a finding about the gene and the disease. The quoted sentences say what the papers report.
neuroblastoma (7 papers, 2020 to 2024). Neuroblastoma (NB) is the most common solid, extracranial childhood tumor. "Further studies have employed computational approaches to identify the immunotherapy targets such as CAMKV in neuroblastoma patients presenting with MYCN or GPC2 amplification in high-risk neuroblastoma." (PMID 36295546, 2022). "Our data suggest a role for DYRK3 as a regulator of the neuroblastoma-specific protein CAMKV, which is also required for neuroblastoma cell proliferation." (PMID 38255303, 2024). "In agreement with a previous report, we observed that CAMKV is highly enriched in neuroblastoma cancer cell lines and in healthy neural tissues." (PMID 38255303, 2024). "CAMKV is a protein highly enriched in neuroblastoma cancer cell lines and in healthy neural tissues." (PMID 38255303, 2024). "CaMKv was found in both membrane and soluble fractions of neuroblastoma cell lines, and plasma membrane (as well as cytoplasmic) staining was detected." (PMID 35965782, 2022). "A recent report identified CaMKv as a potential immunotherapeutic target in MYCN-amplified neuroblastoma, due to its inordinately high expression in these tumors compared to normal human tissues." (PMID 35965782, 2022). "From this analysis, we nominated the unstudied protein CAMKV as a putative immunotherapeutic target for MYCN amplified neuroblastoma." (PMID 32211329, 2020). "Together, these data suggest that in some high-risk neuroblastomas that lack MYCN amplification, MYC can drive CAMKV transcription." (PMID 32211329, 2020). "Together, these data show that CAMKV is a membrane-bound protein in MYCN amplified neuroblastoma with the potential to be targeted using a CAMKV-specific biologic." (PMID 32211329, 2020). "From membrane fractionation and immunohistochemistry, we verified that CAMKV is membranous in MYCN amplified neuroblastoma cell lines and patient-derived xenografts." (PMID 32211329, 2020). "We confirmed that CAMKV is selectively expressed in 7/7 MYCN amplified neuroblastoma cell lines and showed that the transcription of CAMKV is directly controlled by MYCN." (PMID 32211329, 2020). "Our data strongly support the idea that inhibition of DYRK3 and/or CAMKV in neuroblastoma cells could constitute an innovative and highly specific intervention to fight against this dreadful cancer." (PMID 38255303, 2024). "Here, we nominate CAMKV as an immunotherapeutic target for MYCN amplified neuroblastoma, and suggest pursuing the identification of specific human scFv binders to this protein for the creation of antibody-drug conjugate therapeutics that should not cross the blood-brain barrier." (PMID 32211329, 2020). "Finally, the membrane localization of CAMKV was confirmed in MYCN amplified NGP neuroblastoma cells by immunofluorescence." (PMID 32211329, 2020). "Finally, we examined if CAMKV protein expression is selectively expressed in MYCN amplified neuroblastoma cell lines." (PMID 32211329, 2020). "It is reported that CAMKV could as an immunotherapeutic target for MYCN amplified neuroblastoma." (PMID 36158685, 2022). "To investigate whether MYCN protein regulates CAMKV expression, we transiently depleted MYCN from MYCN amplified IMR-05 cells using shRNA and saw a significant reduction in CAMKV mRNA levels (p < 0.005), suggesting that MYCN is required for CAMKV transcription in MYCN amplified neuroblastoma cells." (PMID 32211329, 2020). "We used NCAM1 (CD56), an established cell surface molecule expressed in neuroblastoma as a marker for the plasma membrane and found NCAM1 and CAMKV proteins co-localize on the plasma membrane of NGP cells." (PMID 32211329, 2020).
ovarian carcinoma (2 papers, 2020 to 2021). A malignant neoplasm originating from the surface ovarian epithelium. "Antibody-profiling serum from healthy controls (n = 35), benign controls (n = 12) and ovarian cancer patients across four disease subtypes (n = 80) using the custom protein array showed detectable autoantibodies (Z-score > 0) against all antigens except CAMKV and MAGEB10 (n = 48/50)." (PMID 34681879, 2021).
breast carcinoma (1 paper, 2024). "Moreover, we computed SSES metrics for two genes: CAMKV and MUC2, which have been previously reported to play an important role in mediating proliferation, apoptosis and metastasis of breast cancer cells." (PMID 39003292, 2024).
endometrial cancer (1 paper, 2022). Primary or metastatic malignant neoplasm involving the endometrium (mucous membrane that lines the endometrial cavity). "Using univariate Cox regression and Least absolute shrinkage and selection operator (LASSO), seven kinases (ALPK2, CAMKV, TTK, PTK6, MAST1, CIT, and FAM198B) were identified to establish a prognostic model of endometrial cancer." (PMID 36158685, 2022).
immunodeficient diseases (1 paper, 2022). "The functional capacities of the highly expressed DEGs in the Chinese Simmental cattle mainly focused on inflammatory diseases (CXCL9 and FCRL1), immunodeficient diseases (ADM2, CCL5, and CAMKV), carcinoma (CXCL11, JAKMIP2, GZM, and DNAAF1), and GTP binding and GTPase activity (NUGGC)." (PMID 35495650, 2022).
Intellectual disability (1 paper, 2016). "This suggests a possible link between CaMKv dysregulation and neurodevelopmental disorders associated with intellectual disability, which is of immense interest and warrants further investigation." (PMID 27796283, 2016).
Obesity (1 paper, 2025). Accumulation of substantial excess body fat. "Proteins such as TRPV4 and CaMKV emerge as promising targets for future obesity treatment." (PMID 40076916, 2025).
pituitary adenomas (1 paper, 2025). "Additional genes—PHYHD1, LTBR, MYBPHL, C22orf42, PRR5, ANKDD1A, RAB13, CAMKV, KIFC3, WNT4, and STAT6—were implicated in the invasive behavior of non-functioning pituitary adenomas (NFPAs)." (PMID 39859246, 2025).
cancer (6 papers, 2020 to 2024). A tumor composed of atypical neoplastic, often pleomorphic cells that invade other tissues. "Among the 148 dark kinases included in our analysis, PKMYT1 (in 17 cancers), Mitogen-Activated Protein Kinase 15 (MAPK15) in nine cancers, CaM Kinase Like Vesicle Associated (CAMKV) in 8 cancers), PNCK and STK31 (in seven cancers) were commonly upregulated." (PMID 33801837, 2021). "The most commonly overexpressed CaMK is the pseudokinase CAMKV, which is significantly upregulated in 14 cancer cohorts." (PMID 33205077, 2020). "CAMKV and MUC2 are the most enriched genes in areas of carcinoma (SSES = 1.37 and SSES = 1.29 respectively), whilst NCR1 (synonym: CD335) and CLEC6A, both selectively expressed in Natural Killer cells (NK-cells), are spatially localised to lymph nodes (SSES = 8.59 and SSES = 6.42 respectively)." (PMID 39003292, 2024).
tumor (2 papers, 2019 to 2023). "This analysis underscores the precise involvement of HOXB6, HLA-F, and CAMKV in tumor progression through T cell activation processes in the luminal A subtype." (PMID 38012271, 2023). "The DNA methylation and expression levels of PHYHD1, LTBR, MYBPHL, C22orf42, PRR5, ANKDD1A, RAB13, CAMKV, KIFC3, WNT4 and STAT6 are associated with tumor invasion, and these genes may become the potential genes for targeted therapy." (PMID 31796052, 2019).
CAMKV also shares sentences with these, for which no sentence is quoted: depression (1 paper); insomnia (1); neurodegenerative disease (1); neurodevelopmental disorder (1); psychiatric disorder (1); schizophrenia (1).